INS (insulin)
Diseases named in the same sentence as INS in open-access papers (continued):
Sharing a sentence is not in itself a finding about the gene and the disease.
Insulin resistance (continued). "Insulin resistance and compensatory hyperinsulinemia can induce reproductive diseases related to excessive androgen levels such as PCOS that shows abnormal estrous cycles, as insulin can induce androgen secretion from the adrenal glands and regulate the level of luteinizing hormone." (PMID 38115159, 2023). "The other significant outcome analyzed in the current study was insulin sensitivity which can be measured using several simple surrogate indexes, including the homeostasis model assessment (HOMA), Quantitative insulin sensitivity check index (QUICKI), and Adipose Tissue Insulin Resistance Index." (PMID 37362539, 2023). "It predicted higher insulin resistance (higher HOMA-IR, lower MATSUDA), and increased absolute insulin secretion (AUCins/glu, HOMA-B), but lower insulin resistance-adjusted insulin secretion (relative insulin secretion, ISSI-2) at 1 year postpartum (all p ≤ 0.036)." (PMID 37891561, 2023). "A lack of a standardized universal insulin assays limit their use for routine assessment of insulin resistance in the clinical setting and may have affected our results." (PMID 36900929, 2023). "The results showed that CD36 deletion protected myotubes from insulin resistance in the presence of PA overload, probably because CD36 deletion reduced the uptake of excess LCFAs and alleviated lipid overaccumulation, thus improving the insulin signaling pathway." (PMID 36979708, 2023). "Whether plant protein has a direct effect on insulin action, is not clear, as several nutrients commonly found in plant foods may play a role in mitigating the effects of insulin resistance, including polyphenols, such as genistein." (PMID 37799765, 2023). "However, it was not clear whether it was a direct effect on the insulin signalling pathway or mitochondrial dysfunction Therefore, this calls for more studies aiming at exploring a link between antidepressant-induced-mitochondrial toxicity and risk of developing insulin resistance." (PMID 36860368, 2023). "In addition, the administration of methyltestosterone reduced glucose uptake during insulin infusions in non-obese pre-menopausal women, suggesting that hyperandrogenemia induces insulin resistance." (PMID 38068890, 2023). "Additionally, the 8-week HFHS diet did not lead to the development of glucose intolerance or insulin resistance in either group, nor were changes observed in glycemia or plasma insulin levels in both fasted and fed states." (PMID 37189379, 2023). "In addition, stimulation of the P2Y2R suppressed basal and insulin-induced phosphorylation of AKT, accompanied by decreased GLUT4 membrane translocation and glucose uptake in mature adipocytes, suggesting a role of P2Y2R in insulin resistance." (PMID 38141758, 2023). "In addition, SIRT1 promotes insulin expression by activating the expression of NeuroD and MafA (Zhou, Tang & Chen, 2018) SIRT1 and its activators reduce insulin resistance and diabetic complications and are thus potentially effective therapeutic targets for type 2 diabetes (T2D)." (PMID 36815979, 2023). "The results showed that PTR could alleviate pancreatic tissue damage, significantly decrease fasting blood glucose (FBG), fasting serum insulin (FINS), homeostasis model assessment insulin resistance (HOMA-IR), urinary glucose (UGLU), and urinary albumin/creatinine ratio (UACR)." (PMID 38005193, 2023). "Although there are currently no medications specifically approved to treat insulin resistance, HOMA-IR provides an effective way to monitor lifestyle interventions designed to improve insulin sensitivity, such as weight loss, exercise, and diet replacement interventions." (PMID 38115031, 2023). "Some studies have shown that upregulation of CD36 is associated with insulin resistance, suggesting that CD36 may be a negative mediator of insulin sensitivity." (PMID 36979708, 2023).
Insulin resistance (continued). "There are inadequate data to determine whether a predominant defect in insulin secretion without excess insulin resistance is related to adverse perinatal outcomes." (PMID 38110524, 2023). "The fat tissue distribution is considered the crucial factor in developing insulin resistance and, consequently, T2DM, independent from the stage of obesity, and those with a high proportion of visceral fat and limited abdominal subcutaneous fat are more insulin-resistant." (PMID 36768056, 2023). "The heightened state of insulin resistance during pregnancy returns to the pre-pregnancy state after delivery, and as such, these women may not be sufficiently resistant to insulin 4–6 years post-pregnancy to observe an appreciable change in glycemia." (PMID 37892496, 2023). "To examine whether the insulin-sensitizing action of rcREG3A is effective in non-genetically obese mouse models with insulin resistance, we tested the effect of rcREG3A on glucose metabolism in C57BL/6 WT mice with HFD-induced prediabetes." (PMID 36918710, 2023). "Furthermore, we did not measure plasma insulin concentrations and, therefore, were not able to calculate indices of insulin resistance, which have been shown to correlate with oxidative stress in several studies." (PMID 37190046, 2023). "Insulin resistance develops when insulin fails to exert its full effect on target tissues." (PMID 37620954, 2023). "They couldn’t find a significant difference in miR-146 expression level between the participants with and without insulin resistance, but the miR-146a and miR-146b had a significant correlation with body fat percentage, BMI, and insulin sensitivity index." (PMID 36859176, 2023). "Insulin resistance increases hepatic de novo lipogenesis, enhances adipose tissue lipolysis with subsequent elevation in circulating free fatty acids (FFA), impairs the transcapillary passage of insulin to target tissues, and decreases microvascular blood flow and expansion of the capillary network." (PMID 36678603, 2023). "Insulin resistance could not be assessed in our study because of the lack of necessary data (i.e., fasting insulin, glucose, or HOMA levels)." (PMID 36766605, 2023). "However, long-lasting insulin resistance can contribute to the conversion to T2D if insulin secretion does not compensate insulin resistance." (PMID 37795366, 2023). "Since insulin levels and glucose concentrations are the only measurements needed to calculate HOMA-IR and HOMA-B, they have become the most widely used surrogate indicators, providing valuable insights into insulin resistance, b-cell function, and glucose metabolism." (PMID 36788521, 2023). "While unilateral intrastriatal 6-OHDA administration has been shown to affect serum insulin levels (early increase in glucose tolerance test) and striatal insulin signaling, it has not induced peripheral insulin resistance, at least not at the 6-week post-lesion time point." (PMID 36979662, 2023). "It is not known, though less likely, if the change of insulin level and insulin resistance may impact on the effects of CXCL5 inhibition on angiogenesis in the different animal models." (PMID 37420254, 2023). "On the one hand, the effect of obesity on diabetic complications may be two-sided, with both positive and negative effects, and FCP was correlated with both insulin resistance and insulin secretion defects." (PMID 37096235, 2023). "Another explanation may be related to insulin resistance as current recommendations from the American College of Obstetricians and Gynecologists (ACOG) include improving insulin sensitivity prior to pregnancy via treatments like metformin, which in turn can decrease circulating androgens." (PMID 37992405, 2023). "Finally, the A/L ratio was not compared with other known markers of insulin sensitivity/insulin resistance, such as HOMA-IR." (PMID 36676079, 2023).
Insulin resistance (continued). "We had some methodological restrictions, and it was not possible to obtain sufficient plasma to measure insulin, and, therefore, the effect of the ingredients on insulin resistance could not be evaluated." (PMID 37509800, 2023). "However, the adipose tissue insulin resistance index (Adipo-IR) is a simple and inexpensive surrogate marker calculated from basal NEFA and insulin concentrations which correlates closely with clamp-derived measures and in vitro adipocyte insulin action." (PMID 37491534, 2023). "Finally, the etiology of T2DM, such as the insulin secretion capacity and insulin resistance, was not determined, since the serum insulin concentrations were not measured." (PMID 37049581, 2023). "In experimental studies, insulin sensitivity has been measured using the hyperinsulinemic clamp, the hepatic insulin sensitivity index, or a 75 g oral-glucose tolerance test (OGTT) whereas insulin resistance has been measured via the homeostatic model assessment of insulin resistance (HOMA-IR)." (PMID 37339144, 2023). "By the calculation of FBG and serum insulin levels, treatment with the LS extract (1000 mg/kg) remarkably attenuated HOMA-IR as compared with that of the DM control, and its effect was similar to that of glibenclamide, indicating the potent effect of the LS extract in reducing insulin resistance." (PMID 36625086, 2023). "Second, although the study selected healthy individuals as representatives, it did not test their inflammatory markers or insulin status, and could not exclude the situation of inflammation or insulin resistance in the selected population." (PMID 36839246, 2023). "Further, TyG index does not need an insulin assay thus is less costly than other estimates for IR such as homeostasis model assessment-estimated insulin resistance (HOMA-IR), thus could have wider applications." (PMID 36793924, 2023). "However, if this response fails to compensate and insulin resistance persists, β-cell proliferation will decrease along with insulin secretion and T2D will develop." (PMID 37941908, 2023). "Continuous exposure to increased insulin levels downregulates plasma membrane insulin receptor expression, which in turn augments insulin resistance; however, we did not obtain any evidence suggesting that prolonged exposure to elevated insulin levels downregulates insulin receptor expression." (PMID 37443824, 2023). "Notably, part of these reports lacked indicator data concerning insulin resistance and insulin sensitivity, which was challenging to explain the negative correlation between blood Metrnl and FBG." (PMID 36911663, 2023). "Additionally, BMI, waist circumference, fat mass, fat-free mass, systolic and diastolic blood pressure, insulin resistance (measured by HOMAIR), fasting blood glucose, insulin, HbA1c, triglycerides, total cholesterol, LDL cholesterol, and HDL cholesterol were all decreased following VLCKD." (PMID 37892542, 2023). "Western blotting results showed that both insulin and KRA-533 could significantly inhibit the expression of ZFYVE28; however, under PA-induced insulin resistance, only KRA-533 had an inhibitory effect on ZFYVE28 expression while the inhibitory effect of insulin disappeared." (PMID 37884540, 2023). "However, in the case of obesity-induced insulin resistance, these cells no longer respond to insulin’s metabolic effects and the systemic FA flux is exacerbated as insulin can no longer inhibit lipolysis." (PMID 37432265, 2023). "Given that we see increased insulin levels with increased activation of YAP, this could suggest that the activation of YAP is the initiating pathway that may be causing insulin resistance and not the other way around." (PMID 37198225, 2023). "However, non-fasted serum glucose and insulin levels, HOMA-IR (insulin resistance index), insulin tolerance and glucose tolerance were not significantly different between genotypes." (PMID 39916931, 2023).
Insulin resistance (continued). "In pathological conditions of insulin resistance, insulin fails to regulate liver metabolism, resulting in excessive glucose production alongside increased lipid synthesis; consequently, NAFLD is associated with insulin-resistance." (PMID 37377968, 2023). "Moreover, the absence of effects of maternal dysmetabolism on insulin sensitivity with development contrasts with the documented impact of maternal obesity on insulin resistance later in life in animals and humans." (PMID 38201896, 2023). "Type I DM results from a lack of insulin secretion, not insulin resistance." (PMID 37194835, 2023). "However, the mechanisms that mediate insulin secretion defect and insulin resistance have not yet been fully elucidated." (PMID 37077360, 2023). "Insulin resistance is a pathological condition in which cells do not normally respond to insulin." (PMID 37239168, 2023). "The percentage of patients treated with insulin injections was lower in the improved group than in the progressive group, suggesting that patients in the improved group had an insulin-resistance state with more frequent dyslipidemia, rather than an insulin-dependent state." (PMID 37513666, 2023). "Additionally, it reduces the homeostatic model assessment levels of insulin resistance (WMD = −1.47 [−3.14, 0.19]; p = 0.08; I2 = 56.3%), fasting glucose (WMD = −0.30 [−0.75, 0.15]; p = 0.19; I2 = 84.4%), and fasting insulin (WMD = −2.95 [−8.64, 2.74]; however, these results are non-significant." (PMID 36961066, 2023). "However, new tools for evaluating IR have been developed in recent years, which greatly facilitate their clinical application, such as the homeostasis model assessment of insulin resistance (HOMA-IR) and the Quantitative Insulin Sensitivity Check Index (QUICKI)." (PMID 38179048, 2023). "However, fasting insulin concentrations and calculated Homeostatic Model Assessment for Insulin Resistance (HOMA-IR) were increased with FFC feeding in WT, but not Rip3K51A/K51A, mice." (PMID 38161978, 2023). "An important correlation between enhanced insulin sensitivity and both plasma ApoC-III and TG suppression was also reported through the effects of the antisense APOC3 inhibitor — volanesorsen (ISIS 304801) — on TG levels and insulin resistance in patients with type 2 diabetes." (PMID 36689070, 2023). "Furthermore, the lower metabolic clearance rate of insulin (MCRI) often observed with insulin resistance could be an important initial metabolic change that accelerates obesity and insulin resistance." (PMID 37373776, 2023). "However, in a vulnerable subset of the population insulin secretion fails to sufficiently increase in response to insulin resistance leading to T2D." (PMID 36814640, 2023). "In summary, although the HF+n-3 intervention did not improve hyperglycemia, it could significantly alleviate HF-induced insulin resistance, while the HF+n-6 diet did not have such a beneficial effect on insulin sensitivity." (PMID 38139090, 2023). "We hypothesized that skeletal muscle degeneration due to FGR and abnormal insulin signaling would lead to insulin resistance without obesity in young offspring." (PMID 36649006, 2023). "Interestingly, various obesity related factors have been shown to upregulate DDIT4, which may contribute towards the development of insulin resistance, and genetic inhibition of the DDIT4 gene has been observed to impair insulin sensitivity." (PMID 36662841, 2023). "Importantly, the insulin resistance seen in HFD fed Mboat7ASKO mice appears to be peripheral in nature given the blunted insulin-induced glucose disappearance with no change to insulin-induced suppression of hepatic glucose production." (PMID 36806709, 2023). "This inflammatory environment promotes insulin resistance by activation of nuclear factor kappa-light-chain-enhancer of activated B cells (NF-κB) and c-Jun N-terminal kinase (JNK) pathways that, in turn, lead to the decline of insulin secretion by pancreatic b-cells." (PMID 37239990, 2023).
Insulin resistance (continued). "Additionally, plasma insulin and random blood glucose levels were significantly increased compared to the control group, indicating successful establishment of the T2DM model with insulin resistance, hyperinsulinemia and elevated blood glucose." (PMID 37143104, 2023). "From a different perspective, the importance of psychological stress is also not to be neglected as it is known for decreasing insulin sensitivity and increasing insulin resistance and, therefore, may be important in the development or the onset of T1DM." (PMID 37510181, 2023). "In T2DM, insulin resistance arises due to decreased expression levels of insulin resistance, the altered phosphorylation status of insulin receptor substrate proteins, and impaired activation of axonal growth-related pathways, so providing insulin also fails to alter DPN." (PMID 38264279, 2023). "Sertraline increased circulating NEFAs at baseline in our study, potentially consistent with increased serotonin-induced activation of lipolytic 5-HT2B receptors in WAT, particularly as sertraline did not alter other markers of insulin resistance such as insulin or glucose concentrations." (PMID 37537371, 2023). "On the account that some processes link autophagic disorders with ER stress responses and impaired insulin signaling through activating the JNK/IKK signaling pathways, ER stress, autophagy, and altered adipose tissue metabolism are all shown to be related to the development of insulin resistance." (PMID 37876013, 2023). "Interestingly, peripheral insulin sensitivity is not affected even with the sign of insulin resistance in the brain." (PMID 37511207, 2023). "Interestingly, it has been reported that glucose entrance through GLUT1 with activation of the hexosamine pathway may decrease the insulin-mediated glucose transport through GLUT4, leading to insulin resistance." (PMID 37540242, 2023). "With insulin resistance, skeletal muscles do not respond to insulin at its normal concentration, thereby determining an increase in glucose levels and a compensatory increase in insulin production in response to this." (PMID 36860209, 2023). "As insulin rapidly modulates protein phosphorylation to enact its functional outcomes such as GLUT4 translocation, defects in insulin-regulated phosphorylation could lead to insulin resistance." (PMID 36808134, 2023). "In macrophage-adipocyte co-culture systems, inactivation of AMPKα1 has been shown to inhibit insulin signalling and glucose uptake and upregulate JNK phosphorylation in adipocytes, indicating the activation of the JNK pathway, which is a key inflammatory pathway leading to insulin resistance." (PMID 38066566, 2023). "In fact, as the utilization of glucose in the CNS is largely insulin independent, impairment of glucose tolerance in the absence of insulin resistance may be a relatively specific marker for reduced CMRglc." (PMID 37163733, 2023). "Concerning the assessment of insulin sensitivity, gold standard techniques, such as a hyperinsulinemic-euglycemic clamp, might capture more accurately the relationship between CHIT1 circulating activity and insulin resistance in children with obesity." (PMID 36670674, 2023). "mTORC1 also regulates insulin signaling via Grb10 (growth factor receptor-bound protein 10), which inhibits threonine phosphorylation of insulin/IGF receptors and blocks PI3K/Akt signaling, thereby disrupting the IRS axis leading to insulin resistance and increased hyperglycemia." (PMID 37894760, 2023). "Lowered insulin sensitivity and insulin resistance are signs that the body is not using insulin as efficiently as it should, which might be indicated by high fasting glucose (hyperglycemia) or high fasting insulin levels (hyperinsulinemia)." (PMID 37465091, 2023). "However, when considering genes that showed substantial fold changes, but not passed the FDR cut-off, we observed pathways related to insulin signaling and insulin resistance to be affected." (PMID 36840844, 2023).